ANKZF1 (ankyrin repeat and zinc finger peptidyl tRNA hydrolase 1)
Description:
Endonuclease that cleaves polypeptidyl-tRNAs downstream of the ribosome-associated quality control (RQC) pathway to release incompletely synthesized polypeptides for degradation. The RQC pathway disassembles aberrantly stalled translation complexes to recycle or degrade the constituent parts. ANKZF1 acts downstream disassembly of stalled ribosomes and specifically cleaves off the terminal 3'-CCA nucleotides universal to all tRNAs from polypeptidyl-tRNAs, releasing (1) ubiquitinated polypeptides from 60S ribosomal subunit for degradation and (2) cleaved tRNAs. ANKZF1-cleaved tRNAs are then repaired and recycled by ELAC1 and TRNT1. Also plays a role in the cellular response to hydrogen peroxide and in the maintenance of mitochondrial integrity under conditions of cellular stress.
Synonyms: ZNF744; FLJ10415; Vms1
Tractability: PROTAC: ubiquitination databases record sites on it; its protein half-life has been measured.
Gene: Protein-coding gene on chromosome 2 (219,229,769 to 219,236,679, forward strand). Ensembl gene ENSG00000163516.
Subcellular location: Cytoplasm
Subcellular location (Human Protein Atlas): Nucleoplasm; Cytosol; Nuclear bodies
Pathways (Reactome):
Metabolism of proteins: Ribosome Quality Control (RQC) complex extracts and degrades nascent peptide
Gene Ontology:
Molecular function: catalytic activity, acting on a tRNA; protein binding; RNA endonuclease activity
Biological process: cellular response to hydrogen peroxide; protein quality control for misfolded or incompletely synthesized proteins; rescue of stalled ribosome; ERAD pathway
Cellular component: cytoplasm; membrane; cytosol
Genetic constraint (gnomAD): Loss-of-function variants: 85 observed, 90.45 expected, observed/expected ratio (o/e) 0.94, 90% interval 0.79 to 1.12. The upper end of that interval is the gene's LOEUF score, 1.12, which puts it in group 4 of 6, group 1 being the genes least tolerant of losing a copy. Missense variants: 893 observed, 967.5 expected, observed/expected ratio (o/e) 0.92, 90% interval 0.87 to 0.98. Synonymous variants: 331 observed, 376.71 expected, observed/expected ratio (o/e) 0.88, 90% interval 0.8 to 0.96.
Gene-disease validity (ClinGen):
ClinGen rates the evidence that ANKZF1 causes each of these diseases.
inflammatory bowel disease (inheritance undetermined): Disputed. A spectrum of small and large bowel inflammatory diseases of unknown etiology.
Homologues: Orthologues: chimpanzee ANKZF1 (98% identical), macaque ANKZF1 (94% identical), dog ANKZF1 (83% identical), pig ANKZF1 (81% identical), rat Ankzf1 (79% identical), rabbit ANKZF1 (79% identical), mouse Ankzf1 (78% identical), guinea pig ANKZF1 (76% identical), zebrafish ankzf1 (41% identical), tropical clawed frog ankzf1 (40% identical), Caenorhabditis elegans vms-1 (22% identical).
Diseases named in the same sentence as ANKZF1 in open-access papers:
ANKZF1 is named in the same sentence as 16 diseases in open-access papers, as found by Europe PMC text mining. Sharing a sentence is not in itself a finding about the gene and the disease. The quoted sentences say what the papers report.
colon cancer (5 papers, 2020 to 2024). "Knockdown of ANKZF1 was recently shown to inhibit proliferation, migration, and invasion of colon cancer cells and its association with poor survival has been reported in colorectal cancer." (PMID 39193365, 2024). "In support of our observation, a previous study showed that ANKZF1 plays an important role in angiogenesis in colon cancer." (PMID 37158785, 2024). "Some bioinformatics analyses have proved that ANKZF1 based genes signature can predict the prognosis of patients with colon cancer, renal cell carcinoma, and prostate cancer." (PMID 35141153, 2021). "The upregulation of ANKZF1 has been reported to be related to poor OS and DFS in colon cancer." (PMID 35123420, 2022).
colon adenocarcinoma (3 papers, 2022). "Another study identified ANKZF1 and DLAT as glycolysis-related genes to predict the survival in colon adenocarcinoma patients." (PMID 35924040, 2022).
glioblastoma (2 papers, 2025 to 2026). The most malignant astrocytic tumor (WHO grade IV). "Subcutaneous or intracranial implanted tumour models showed that shRNA‐mediated downregulation of ANKZF1 results in reduced malignant progression of glioblastoma cells." (PMID 38949989, 2025). "A recent study investigated the mechanism of ANKZF1 in mitochondrial proteostasis and its impact on glioblastoma multiforme (GBM) progression." (PMID 38798583, 2026).
clear-cell renal cell carcinoma (1 paper, 2025). "Similarly, in clear-cell renal cell carcinoma (ccRCC), NAT10 acts through ankyrin repeat and zinc finger peptidyl tRNA hydrolase 1 (ANKZF1) to increase the nuclear localization of yes1-associated transcriptional regulator (YAP1), thereby driving tumor progression and lymphangiogenesis." (PMID 41316475, 2025).
glioma (1 paper, 2026). A benign or malignant brain and spinal cord tumor that arises from glial cells (astrocytes, oligodendrocytes, ependymal cells). "A murine GBM model exhibited analogous RQC pathway alterations, with increased NEMF and decreased ANKZF1 expression in transplanted SB28 gliomas compared to normal brain tissue." (PMID 38798583, 2026).
pancreatic cancer (1 paper, 2022). "Furthermore, the qPCR results indicated the mRNA expression levels of JMJD6, ANKZF1, CITED2, and ENO3 was obviously decreased in pancreatic cancer cells versus the normal pancreatic ductal epithelial cells, whereas those of LDHA, TES, and SIAH2 were oppisite." (PMID 35935823, 2022).
cancer (9 papers, 2020 to 2026). A tumor composed of atypical neoplastic, often pleomorphic cells that invade other tissues. "ANKZF1, an ankyrin repeat and zinc finger domain-containing protein, is implicated in tumor progression and glycolysis across cancers." (PMID 41210694, 2025). "This, combined with our data, suggests that balanced ANKZF1 expression and activity are vital for cancer proliferation." (PMID 38798583, 2026). "HPA analysis showed that the protein levels of LDHA and TES were highly upregulated in cancer tissues compared to normal pancreatic tissue, while those of NDST1, ANKZF1, and SIAH2 were significantly decreased in cancer tissues." (PMID 35935823, 2022). "Numerous other genes such as ESPL1, DOCK8, ARID3A, PFKFB4, ANKZF1, BANP and GRB7 showed elevated expression rates, some of which are known or suspected to be involved in cancer development and/or progression." (PMID 37193047, 2022). "Notably, the expression profile of various RQC factors (e.g., ASCC3, ABCE1, ANKZF1, and VCP) is dysregulated in cancer." (PMID 38798583, 2026). "Furthermore, the dysregulation of RQC factor expression in cancer cells, including that of ASCC3, ANKZF1, ABCE1, and VCP, highlights the intricate nature of their roles in cancer." (PMID 39315278, 2024). "Due to the lack of sufficient research, the actual role of ANKZF1 in cancer and glycolysis is unclear, and it is worthy of further investigation." (PMID 34595101, 2021).
tumor (8 papers, 2020 to 2025). "Five GRGs (ABCB6, ANKZF1, B3GAT3, KIF20A and STC2) were dysregulated in tumor samples and were independently associated with the prognosis of HCC." (PMID 35123420, 2022). "N-acetyltransferase 10 (NAT10)-ankyrin repeat and zinc finger peptidyl tRNA hydrolase 1 (ANKZF1) axis promotes tumor progression and lymphangiogenesis of ccRCC by enhancing the nuclear import of Yes1-associated transcriptional regulator (YAP1), and upregulating expression of VEGF-C/-D." (PMID 41511312, 2025). "The protein expression of CD44 and ANKZF1 were low in both normal and tumor tissues." (PMID 33287763, 2020). "Compared with normal kidney tissues, antibody stainings for ANKZF1, CD44, IDUA, KIF20A, PLOD2, and VCAN were high in ccRCC tumor tissues, whereas they were low for CHST6, HS6ST2, NDST3 and FBP1." (PMID 33836688, 2021).
infection (2 papers, 2021 to 2022). The state of being infected such as from the introduction of a foreign agent such as serum, vaccine, antigenic substance or organism. "Among the highly upregulated genes in both infection groups were ESPL1, DOCK8, ARID3A, PFKFB4, ANKZF1, BANP and GRB7, all of which exhibited a log2 fold change of ≥1.5." (PMID 37193047, 2022).
ANKZF1 also shares sentences with these, for which no sentence is quoted: colorectal cancer (3 papers); prostate carcinoma (2); Alzheimer disease (1); myocarditis (1); neurodegenerative disease (1); renal cell carcinoma (1); viral myocarditis (1).